LINC00858 (long independently transcribed non-coding RNA 858)
Synonyms: CRCAL-2; LNMAT2
Gene: Long non-coding RNA gene on chromosome 10 (84,267,747 to 84,294,659, forward strand). Ensembl gene ENSG00000229404.
Diseases named in the same sentence as LINC00858 in open-access papers:
LINC00858 is named in the same sentence as 17 diseases in open-access papers, as found by Europe PMC text mining. Sharing a sentence is not in itself a finding about the gene and the disease. The quoted sentences say what the papers report.
colorectal cancer (6 papers, 2018 to 2022). A primary or metastatic malignant neoplasm that affects the colon or rectum. "Overexpression of LINC00858 has been reported to promote proliferation and migration of non-small cell lung cancer and colorectal cancer by acting as a competing endogenous RNA." (PMID 36528654, 2022). "Previous studies have shown that LINC00858, a novel lncRNA, is upregulated in several cancers and functions as a tumor promoter in colorectal cancer, non-small cell lung cancer, and osteosarcoma." (PMID 34232111, 2021). "Up-regulation of four lncRNAs, hereby named colorectal cancer associated lncRNA (CRCAL)-1 [AC021218.2], CRCAL-2 [LINC00858], CRCAL-3 [RP11-138J23.1] and CRCAL-4 [RP11-435O5.2], was further validated by real-time RT-PCR in 139 colorectal neoplasms and matched NM tissues." (PMID 29330370, 2018). "LINC00858 expression was observed to be up-regulated in colorectal cancer (CRC), osteosarcoma and non-small cell lung cancer (NSCLC) tissues, and associated with poor prognosis, which is in line with our hypothesis, and it exerted its functional effect through the miR-22-3p/YWHAZ axis in CRC." (PMID 32419983, 2020).
gastric cancer (4 papers, 2021 to 2024). A primary or metastatic malignant neoplasm involving the stomach. "In our study, we found that knockdown of LINC00858 suppressed migration and invasion of GC cells as well as primary cells isolated from a fresh gastric cancer sample." (PMID 36528654, 2022). "Given that LINC00858 plays an important role in the metastasis of gastric cancer both in vitro and in vivo, we first detected the expression of LINC00858 via fractionation of cytoplasmic and nuclear RNA." (PMID 36528654, 2022). "Multivariate analysis revealed that differentiation state, infiltration of peritumoral tissues, TNM stage, and LINC00858 expression were all independent prognostic factors in gastric cancer." (PMID 36528654, 2022). "Literatures published recently revealed that LINC00858 was found to play key roles in multiple types of cancers including Wilms’ tumor, ovarian cancer, colon cancer, gastric cancer, hepatocellular carcinomas, and osteosarcomas." (PMID 34760693, 2021). "Third, we isolated a primary gastric cancer cell line and explored the roles of LINC00858." (PMID 36528654, 2022). "Besides, LINC00858 facilitated gastric cancer cell metastasis, which could be regulated by transcription factor YY1." (PMID 38410123, 2024).
non-small cell lung carcinoma (4 papers, 2019 to 2022). A group of at least three distinct histological types of lung cancer, including non-small cell squamous cell carcinoma, adenocarcinoma, and large cell carcinoma. "Recent studies have indicated that HMGA2 and LINC00858 function as ceRNA to promote lung cancer progression and MTAT rs1061451 was a protective factor of non-small-cell lung cancer (NSCLC)." (PMID 31885738, 2019).
colon cancer (3 papers, 2021 to 2022). "Initially, LINC00858 was found to be upregulated in colon cancer and its silencing was observed to inhibit proliferative, migrated, and invasive capabilities of colon cancer cells." (PMID 35468892, 2022). "SW480 and HCT166 cells were selected for subsequent experiments due to their higher LINC00858 expression among the colon cancer cell lines." (PMID 35468892, 2022). "LINC00858 is upregulated in colon cancer, which can enhance the proliferative and invasive abilities and metastatic potential." (PMID 35468892, 2022). "For elucidating the mechanism of LINC00858 in colon cancer, LncMAP was used to predict the possible binding proteins of LINC00858." (PMID 35468892, 2022). "In sum, these results indicated an upregulation of LINC00858 expression in colon cancer, and its knockdown can reduce the proliferative, migrated, and invasive abilities of colon cancer cells while increasing cancer cell apoptotic ability." (PMID 35468892, 2022). "Moreover, we observed higher LINC00858 expression in the four used colon cancer cell lines (HCT166, SW480, Caco2, and SW620) relative to that in NCM460 normal colon cell line." (PMID 35468892, 2022). "Next, we explored the involvement of the LINC00858/RAD21/PCNP axis in colon cancer pathogenesis." (PMID 35468892, 2022). "Using web-based bioinformatics tool GEPIA, highly-expressed LINC00858 was found to in colon cancer." (PMID 35468892, 2022). "Consistently, accruing evidence has documented the oncogenic role of LINC00858 in colon cancer." (PMID 35468892, 2022). "Furthermore, we demonstrated that LINC00858 could upregulate PCNP transcription in colon cancer by recruiting the transcription factor RAD21." (PMID 35468892, 2022). "LINC00858 reportedly regulates HNF4α and WNK2 to produce a tumor-promoting function in colon cancer." (PMID 35468892, 2022). "In order to study the effects of LINC00858 on the tumorigenicity of colon cancer cells by regulating the RAD21/PCNP/STAT3/5 axis in vivo, we injected SW480 cells transduced with adenovirus carrying oe-NC + sh-NC, oe-LINC00858 + sh-NC, oe-LINC00858 + sh-RAD21, oe-LINC00858 + sh-PCNP into nude mice." (PMID 35468892, 2022). "In the current study, we set out to establish if LINC00858 affected the progression of colon cancer and revealed that LINC00858 could recruit RAD21 to regulate PCNP-mediated STAT3/5 signaling pathway, thereby promoting the development of colon cancer." (PMID 35468892, 2022). "Overall, the results obtained in the current study demonstrated that LINC00858 affects the progression of colon cancer and revealed that LINC00858 is able to recruit RAD21 to upregulate PCNP, which contributes to STAT3/5 signaling activation, thereby promoting the development of colon cancer." (PMID 35468892, 2022). "As shown by Western blot assay, the overexpression or knockout of LINC00858 in SW480 and HCT166 cells did not affect the expression of RAD21, suggesting that LINC00858 did not directly regulate the expression of RAD21 to participate in the colon cancer development." (PMID 35468892, 2022).
lung adenocarcinoma (1 paper, 2017). A carcinoma that arises from the lung and is characterized by the presence of malignant glandular epithelial cells. "Recently, Xu and his colleagues has reported that LINC00858 is highly expressed in lung adenocarcinoma (5.23-fold than normal lung tissues), while until now, the relevance between LINC00858 expression and NSCLC tumorigenesis has not been elaborated yet." (PMID 28177876, 2017).
tumor (12 papers, 2017 to 2025). "The expression of LINC00858 was significantly upregulated in tumor tissues compared with normal tissues in both GC and CRC cohort and was therefore selected for further analysis." (PMID 36528654, 2022). "Furthermore, for TCGA tumors with the GTEx database as controls, LINC00858 was significantly upregulated in ten cancer types including GC and further validated in paired tumor and adjacent normal tissues from TCGA." (PMID 36528654, 2022). "In NSCLC patients, high expression of LINC00858 closely correlated with tumor progression." (PMID 28177876, 2017).
cancer (8 papers, 2020 to 2023). A tumor composed of atypical neoplastic, often pleomorphic cells that invade other tissues. "Functional analysis suggested that LINC00858 depletion attenuated the migration, and invasion of cancer cells in vitro and suppressed the metastasis of xenografted tumors in vivo." (PMID 36528654, 2022). "In these cancers, LINC00858 contributes to cell proliferation, migration, and invasion by acting as a competing endogenous RNA that binds to microRNAs." (PMID 34232111, 2021). "LINC00858 was overexpressed in cancer cells compared with GES1 cells." (PMID 36528654, 2022). "In addition, recent studies have found that lncRNA LINC00858 can directly repress the expression of WNK2 in cancer cells and contribute to cancer progression." (PMID 36123332, 2022).
LINC00858 also shares sentences with these, for which no sentence is quoted: bladder cancer (20 papers); osteosarcoma (3); hepatocellular carcinoma (2); lymph node metastasis (2); ovarian carcinoma (2); adenoma (1); colorectal neoplasm (1); esophageal cancer (1); myeloma (1); Wilms tumor (1).